NNMT (nicotinamide N-methyltransferase)
Diseases named in the same sentence as NNMT in open-access papers (continued):
Sharing a sentence is not in itself a finding about the gene and the disease.
tumor (121 papers, 2009 to 2026). "These include macrocyclic peptides as allosteric inhibitors, alkene-linked bisubstrate inhibitors that mimic NNMT’s natural substrates, and esterase-sensitive prodrugs of bisubstrate inhibitors for improved cellular uptake and tumor-selective activation." (PMID 40723224, 2025). "A growing body of evidence indicates that, beyond clearance of excess vitamin B3, NNMT is implicated in the regulation of multiple metabolic pathways in tumor cells by remodeling cellular epigenetic states and generating active metabolites." (PMID 38254798, 2024). "It has been observed that NNMT expression and activity are frequently elevated in tumor tissue, causing a decrease in the cellular SAM content, which in turn will lead to hypomethylation of genes associated with tumor progression and metastasis." (PMID 38256203, 2024). "NNMT is implicated in regulating tumor proliferation, invasion, and drug resistance by affecting multiple signaling pathways in vivo." (PMID 35756670, 2022). "Overexpression of NNMT in tumor cell and stroma cell both are associated with metastasis and unfavorable survival." (PMID 34539890, 2021). "Second, increased expression of NNMT was associated with increased tumor stage, grade, and mesenchymal molecular subtype." (PMID 33446144, 2021). "We showed that increased expression of NNMT was associated with increased tumor stage, grade, and mesenchymal molecular subtype." (PMID 33446144, 2021). "The overexpression of NNMT promotes metabolism in tumor-associated fibroblasts of the ovary, leading to invasion and metastasis of tumors, and is related to poor prognosis." (PMID 35222522, 2021). "Recent NNMT immunohistochemical investigations in OSCC lesions showed that NNMT overexpression is linked to tumor differentiation." (PMID 23990942, 2013). "We found that NNMT was associated with the tumor stage and that higher NNMT mRNA levels in HCC was significantly associated with shorter DFS time." (PMID 19216803, 2009). "The results of this study indicated that NNMT gene expression is associated with tumor stage and DFS time in HCC cases." (PMID 19216803, 2009). "For instance, it was discovered that overexpression of the miR-449a gene would down-regulate nicotinamide n-methyltransferase (NNMT), a tumor-metabolizing enzyme, and cause an increase in the expression of PTEN, which would inhibit tumor growth, in EGRR-AKT resistant NSCLC cells." (PMID 38169723, 2023). "NNMT encodes proteases involved in the metabolism of various substances and drugs in vivo and is highly expressed in a variety of tumors, correlating with tumor infiltration, distant metastasis, and malignancy." (PMID 37008043, 2022). "Thus, we propose that due to the broad expression of NNMT in primary ccRCC tumours and metastases, its association with patient survival, and its molecular functions, NNMT is a promising drug target in ccRCC." (PMID 35678045, 2022). "Indeed, many studies agree in showing that NNMT overexpression is associated with cell viability and proliferation, cell migration, colony formation ability, and tumor growth in animal models." (PMID 34827592, 2021). "In addition to this, recent studies showed that the enrichment of tumor cell lines with CSCs was significantly associated with the enhanced expression of NNMT." (PMID 34439880, 2021). "NNMT was reported to regulate methylation of tumor-associated genes." (PMID 33193702, 2020). "NNMT expression was significantly associated with tumor stage (P = 0.010) in 120 HCCs." (PMID 19216803, 2009). "However, NNMT expression in OCCC tumor cells may be involved in the association between chemotherapy sensitivity and prognosis." (PMID 40853419, 2025). "This form of vitamin B3 efficiently permeates the brain where the tumor-specific methyltransferase activity of NNMT introduces a positive charge on its pyridine ring." (PMID 41576167, 2026).
tumor (continued). "Integrated analysis of Genotype-Tissue Expression and The Cancer Genome Atlas databases revealed tumor-specific NNMT mRNA upregulation in these malignancies." (PMID 41913584, 2026). "Consistent with the tumor-selective increase in NNMT expression and N1-methylnicotinamide accumulation, the tumor–to–contralateral brain ratio of the 11C-nicotinamide PET signal was increased in dexamethasone-treated mice." (PMID 41576167, 2026). "The fraction of 15N-labeled N1-methylnicotinamide was ~40% of the total pool, showing that NNMT activity in the tumor tissue leads to N1-methylnicotinamide accumulation." (PMID 41576167, 2026). "NNMT is upregulated in various solid tumors, including head and neck cancers, where it contributes to tumor aggressiveness." (PMID 40563615, 2025). "Patients with high NNMT immunoreactivity in the tumor stroma had significantly shorter progression-free survival than those with low NNMT immunoreactivity (p = 0.0115, log-rank test) (data not shown)." (PMID 40853419, 2025). "No deaths occurred in patients with lower levels of NNMT expression in the cytoplasm of tumor cells during the study period, whereas 18% (7 of 39 cases) of patients with higher levels of NNMT expression in the cytoplasm of tumor cells died." (PMID 40853419, 2025). "Together, our data suggested administration of knockdown of SNORA13 suppresses CRC proliferation and tumor growth via repressing protein synthesis and inhibiting NNMT level." (PMID 40529507, 2025). "All NNMT inhibitors were able to induce a significant (p < 0.05) decrease (at least ≥50%) in the levels of MNA compared to controls for all tumor cells." (PMID 41301471, 2025). "Further analyses will be carried out to clarify the molecular mechanisms responsible for the aggressive tightening of the tumor cell phenotype, where NNMT participation is believed to be involved." (PMID 41301471, 2025). "For example, a study using a mouse model of ovarian cancer showed decreased tumor burden and tumor cell proliferation in mice treated with an NNMT inhibitor." (PMID 38254784, 2024). "The overexpression of NNMT has been widely observed in various tumor types, correlating with tumor development and progression." (PMID 38809277, 2024). "For instance, the knockdown of NNMT in tumor cell lines increases the SAM/SAH ratio and global H3K9 and H3K27 trimethylation." (PMID 38254798, 2024). "As found in multiple types of human malignancies, NNMT seems to promote both tumorigenicity and proliferation of tumor cells." (PMID 38504052, 2024). "Other genes were modulated in a different way in all three SCCs (NMNAT1, NMNAT2, NADSYN1, SIRT3, and CD38) or in two tumor types (NNMT, NMNAT3, ENPP2, PNP, and SIRT1)." (PMID 38254798, 2024). "Another study showed that the use of an NNMT inhibitor reduced tumor cell viability and induced cytotoxicity in 2D/3D clear cell renal carcinoma-derived tumor models." (PMID 38254784, 2024). "Inhibiting NNMT activity or expression holds promise as a potential therapeutic approach to interfere with tumor growth and metastasis." (PMID 38809277, 2024). "NNMT can influence several epigenetic enzymes, such as histone deacetylase sirtuins and NNMT expression, and is significantly positively correlated with both stromal and immune components, resulting in a tumor-promoting microenvironment." (PMID 38254784, 2024). "The ccRCC renal tubule cells showed a high expression of the oncogene nicotinamide N-methyltransferase and a significantly high degree of tumor heterogeneity." (PMID 38287102, 2024). "The acquisition of stem cell properties induced by NNMT overexpression is another mechanism involved in treatment resistance and tumor relapse." (PMID 39295619, 2024). "On one hand, NNMT is positively regulated with autophagy, and knockdown of NNMT leads to an increase in autophagic activity, affecting the survival and growth of tumor cells." (PMID 39035994, 2024).
tumor (continued). "Among these, C1 NNMT+ CAEPCs were highlighted as a critical therapeutic target for promoting tumor differentiation." (PMID 39840054, 2024). "We found that a knock-down of NNMT reduced the proliferation in in vitro experiments and in vivo tumor growth, opening up the possibility of stromal-directed treatment approaches as part of LGSC treatment." (PMID 38014221, 2023). "NNMT inhibitors derived from methylquinolinium (MQ) such as 5-amino-1MQ, 7-amino-1MQ, and 2,3-diamino-1MQ have been reported to reduce tumor cell proliferation and improve H3K27 trimethylation levels." (PMID 36672415, 2023). "Targeting NNMT expression reduced the proliferation and self-renewal of mesenchymal GSCs, and reduced tumor growth in vivo." (PMID 37298093, 2023). "Intra-tumoral treatment with an NNMT inhibitor (NNMTi) reduced subcutaneous tumor growth of VOA6406ip1 after 4 weeks of treatment." (PMID 38014221, 2023). "Accordingly, NNMT overexpression was reported in numerous neoplasms, including clear cell renal cell carcinoma, oral squamous cell carcinoma, non-small cell lung cancer, and bladder cancer." (PMID 38201930, 2023). "Although the molecular mechanism of HSCs inducing tumor cells to upregulate NNMT is still unclear, NNMT is a promising prognostic biomarker and therapeutic target for HCC." (PMID 37007125, 2023). "This analysis was performed using specific marker genes: GPX3 and ALDOB for proximal tubular cells and VIM, KRT18, NDUFA4L2, and NNMT for tumor cells." (PMID 37533434, 2023). "NNMT+ tumor cells were the main cell type identified in the PD-1+SMI group and regulation of the intrinsic apoptotic signaling pathway was enriched in this subcluster as analyzed by Metascape." (PMID 37430270, 2023). "NNMT is involved in the carcinogenesis process, promoting tumor progression through two main mechanisms, by altering cellular metabolism and epigenetic remodeling." (PMID 36143291, 2022). "NNMT was again most highly expressed in the tumour cell cluster, confirming its prominent expression in ccRCC tumour tissue." (PMID 35678045, 2022). "The results of H&E and Ki-67 staining revealed that tumor proliferation reduced after NNMT knockdown." (PMID 35884600, 2022). "NNMT participates in the regulation of various metabolic pathways and is involved in tumor progression and metastasis." (PMID 35851575, 2022). "The aim of this review was to report data illustrating NNMT involvement in these tumors, highlighting its contribution to tumor cell phenotype." (PMID 36139012, 2022). "In this review, we intend to provide a comprehensive overview of the roles and functions of NNMT in different tumor types." (PMID 35338115, 2022). "In vivo, NNMT overexpression promoted tumorigenicity to a certain extent, while NNMT knockdown resulted in a smaller tumor volume and tumor weight." (PMID 35851575, 2022). "Inhibition of NNMT expression relatively increased the potential for methylation of LCMT1 and led to a reduction in the risk of tumor formation." (PMID 35884600, 2022). "Since efficient glutamine utilisation, which is essential for ccRCC tumours, depends on NNMT, small‐molecule NNMT inhibitors provide a novel therapeutic strategy for ccRCC and act as sensitizers for combination therapies." (PMID 35678045, 2022). "Although there is some controversy regarding NNMT as a precancerous and prognostic marker, some studies have demonstrated the benefits of NNMT inhibition in both tumor invasion and aggression." (PMID 35884600, 2022). "In order to uncover the function of NNMT in tumor cells, we first carried out the three-dimensional cell culture assay and wound healing assay and found that overexpression of NNMT in HN6 cells promoted cell proliferation and migration." (PMID 36291696, 2022). "We demonstrate that NNMT induces DNA-dependent protein kinase catalytic subunit (DNA-PKcs) homocysteinylation, increases DNA repair, and promotes ccRCC tumor growth." (PMID 35440542, 2022).
tumor (continued). "Mechanistically, NNMT overexpression increases Hcy and K-Hcy modification in tumor cells and promoted tumor proliferation." (PMID 35440542, 2022). "Functionally, we demonstrated that the ectopic expression of NNMT promoted OSCC tumor cell proliferation and migration in vitro." (PMID 36291696, 2022). "Western blotting and immunohistochemistry were used to evaluate the NNMT expression in tumor and normal tissue samples obtained from patients affected by CCA." (PMID 36139012, 2022). "The qRT–PCR results showed higher expression of the NNMT mRNA in iCCA tumor tissues than that in adjacent tissues." (PMID 35851575, 2022). "Compared with the adjacent normal tissues, NNMT was significantly upregulated in tumor tissues of OSCC patients (p < 0.05)." (PMID 36291696, 2022). "As a metabolic enzyme, NNMT is closely linked to the levels of NAM, SAM, 1-MNAM, and SAH in tumor cells." (PMID 35338115, 2022). "Altered levels of NNMT have been detected in various neoplasms, such as gastric, colorectal, pancreatic, etc.." (PMID 36143291, 2022). "Together, these results confirmed that NNMT upregulation induces hyper K-Hcy, which activates DNA-PKcs and promotes tumor growth." (PMID 35440542, 2022). "Expression of NNMT in CAFs, and consequential depletion of SAM, causes widespread changes in gene expression in the tumor stromal cells." (PMID 34073600, 2021). "A further potential effect of increased NNMT expression is a reduction in oxidative stress arising from the rapid proliferation of the tumour biomass." (PMID 34680055, 2021). "Collectively, all these studies underscore the tumor-promoting effects of N-methyltransferases such as NNMT and EZH2 in TAFs." (PMID 34359678, 2021). "On the contrary, NNMT immunostaining was significantly increased in tumor tissue compared to the normal mucosa (p = 0.0014), showing an inverse relationship between protein expression and histological grading (p = 0.0498)." (PMID 34827592, 2021). "In this type of tumor, NNMT compromises leucine carboxyl methyl transferase 1 (LCMT1)-mediated methylation of tumor suppressor protein phosphatase 2 (PP2A) and has been identified as a negative prognostic factor." (PMID 34073600, 2021). "NNMT silencing induced a significant reduction in tumor volume (222.3 ± 65.5 mm3 vs. 981.7 ± 137.5 mm3), showing that the downregulation of this protein in OSCC inhibits tumorigenicity in vivo." (PMID 34827592, 2021). "Results obtained revealed that NNMT upregulation (tumor vs. normal tissue) was markedly higher in ccRCC than in other non-clear cell RCCs." (PMID 34439880, 2021). "Our clinical samples revealed that NNMT is highly expressed in tumor of CRC tissue, especially in tumor stroma." (PMID 34539890, 2021). "In the context of studies aiming to disclose the potential involvement of NNMT in urothelial neoplasms, array analyses were used to profile the expression of tumor and normal-looking tissue samples obtained from patients affected with bladder cancer (BC)." (PMID 34439880, 2021). "Here, we aimed to explore the expression of NNMT on tumor stroma and the molecular mechanism between NNMT expression and tumor metastasis." (PMID 34539890, 2021). "Conversely, inhibition of NNMT activity with shRNA (shNNMT) both reverted the expression of markers of activated TAFs and attenuated their tumor-promoting traits." (PMID 34359678, 2021). "Based on immunohistochemistry, the NNMT protein expression showed to be significantly upregulated within tumor tissues." (PMID 34827592, 2021). "And Ulanovskaya showed that NNMT altered the protein methylation state of tumor cells through regulating cellular SAM/SAH ratios." (PMID 33193702, 2020). "NNMT overexpression is critical in tumor metastasis via its induction of epithelial-to-mesenchymal transition (EMT), which is the transformation of epithelial cells into mesenchymal-like cells and is necessary for invasion and metastasis." (PMID 31652035, 2019).
tumor (continued). "Given that NNMT also affects lipid metabolism which is closely related to tumor survival, we examined the effects of common lipid‐lowering drugs on NNMT expression and found a significant inhibitory effect of statins." (PMID 31294922, 2019). "NNMT is upregulated in many types of solid tumors, suggesting the potential for its use as a tumor biomarker." (PMID 30349486, 2018). "With the facilitation of bioinformatics analyses and validation, we identified some tumor-related genes, such as NNMT, FLI1, GAS6, lncRNA CCAT1, PDCD1LG2, and CD274, as the key regulators in the present tumor-like transformation model." (PMID 28286742, 2017). "Chromatin immunoprecipitation and NNMT promoter luciferase assays revealed that AURKA’s effects on NNMT were caused by PAX3-mediated transcriptional repression and overexpression of NNMT blocked tumor cell invasion in vitro." (PMID 28102366, 2017). "In contrast, overexpression of AURKA in UC5 cells (low expression of AURKA) resulted with down-regulation of NNMT Since NNMT is implicated in invasion and metastases, these results directed our attention to the potential role of AURKA in tumor progression." (PMID 28102366, 2017). "Transfected and control cells were injected into athymic mice in order to evaluate the effect of NNMT silencing on tumor growth." (PMID 23990942, 2013). "The results obtained from silencing and in vivo experiments seem to suggest that NNMT is an important molecule involved in tumor cell proliferation and a potential target for counteracting tumor growth." (PMID 23990942, 2013). "A recent investigation showed that NNMT is strongly expressed in the invasive ccRCC cell lines, and NNMT knockdown efficiently repressed metastasis formation and tumor growth of these cells in vivo." (PMID 23990942, 2013). "Importantly, the authors also demonstrated that tumour-related genes, such as NNMT, FLI1, GAS6, lncRNA CCAT1, PDCD1LG2, and CD274, were key regulators of neoplastic transformation in response to a low multiplicity of oral pathogen infection." (PMID 41228271, 2025). "Additionally, the pharmacokinetics and tumor penetration of current NNMT inhibitors need optimization, and their long-term safety and efficacy in humans remain to be determined." (PMID 40427612, 2025). "Blocking NNMT could increase nicotinamide availability, inhibit Sirt1, and promote senescence, leading to tumor growth suppression." (PMID 40563615, 2025). "Indeed, based on the results obtained from cellular experiments, NNMT seems to be involved in tumor cell proliferation, migration, and resistance to chemotherapy, thus representing a potential target for counteracting tumor growth." (PMID 38504052, 2024). "NNMT is expressed in tumor cells as well as cells in the TME." (PMID 38254784, 2024). "In addition, according to the oncogene Nicotinamide N-Methyltransferase (NNMT) in ccRCC, we found that renal tubule cells, endothelial cells in ccRCC tissues high-expressed NNMT, while the two types of cells in para-tumor tissues barely expressed NNMT." (PMID 38287102, 2024). "Moreover, NNMT downregulation was reported to reduce proliferation and tumor-forming in various cell lines, while enzyme overexpression resulted in enhanced cell viability." (PMID 38397036, 2024). "Interestingly, NNMT gene expression was reported to be notably upregulated in the tumor tissue of RCC patients." (PMID 38397036, 2024). "In GC cases exhibiting high expression levels of the enzyme, variations in the immune-cell composition within the tumor microenvironment suggest that NNMT could promote immune infiltration, potentially serving as a prognostic biomarker." (PMID 38542354, 2024).